PGRMC1 (progesterone receptor membrane component 1)
Diseases named in the same sentence as PGRMC1 in open-access papers (continued):
Sharing a sentence is not in itself a finding about the gene and the disease.
cancer (continued). "Until now, there was no experimental evidence of the functional significance of PGRMC1 as a monomer protein since PGRMC1 has been studied mainly in cancer animal models." (PMID 40732235, 2025). "Experimental studies indicate that PGRMC1 was frequently elevated during cancer and is a gene involved in many metabolic pathways, including lipid metabolism as well as autophagy and cell proliferation, migration, and invasion." (PMID 39519555, 2024). "Cancer cells find several ways to prevent this cell death process as a means of survival, and one such mechanism involves PGRMC1." (PMID 37834119, 2023). "A link between PGRMC1 and tumour migration/invasion has been observed in other types of cancer as well, but this phenomenon remains poorly understood thus far." (PMID 37887342, 2023). "The overexpression of PGRMC1 in cancer cells decreases the labile iron pool, thus protecting the cells from iron-induced ferroptosis." (PMID 37834119, 2023). "We note PGRMC1 is highly expressed in several cancer types, serving to accelerate tumor progression and being associated with poor clinical prognosis." (PMID 37866635, 2023). "This provides an ideal environment for the activation of EGFR by the PGRMC1–heme complex to promote cancer." (PMID 37834119, 2023). "Since the PGRMC1 expression has been shown to be increased in most cancers, it is possible that the hepcidin expression is induced in cancer cells by PGRMC1 as it has been shown in the liver." (PMID 37834119, 2023). "As such, the overexpression of PGRMC1 in cancer cells enhances metabolism and the consequent inactivation of doxorubicin, thereby contributing to chemoresistance." (PMID 37834119, 2023). "Since PGRMC1 is known to promote chemotherapy resistance in different types of cancer, we sought to determine its role in the response to therapy of GBM." (PMID 37887342, 2023). "Perhaps the best-characterized role of PGRMC1 in cancer is modulation of resistance to chemotherapy." (PMID 37887342, 2023). "Previous research has associated decreased expression of PGRMC1 with advanced stages and poorer prognosis, and therefore has been proposed as a potential prognostic biomarker for HCC and various other cancers." (PMID 36980321, 2023). "Previous molecular studies found a clear association between PGRMC1 and the EGFR signalling pathway in cancer." (PMID 37887342, 2023). "The abundant expression of PGRMC1 in advanced stages of CRC suggests its potential role in cancer progression." (PMID 37894441, 2023). "The progesterone receptor membrane component 1 (PGRMC1) is the first identified progesterone-binding membrane protein and has a high expression in various cancer cells." (PMID 35992779, 2022). "The observation that PGRMC1 is overexpressed in many types of cancers was probably the first indication of a relationship between its expression and cell proliferation." (PMID 36497237, 2022). "Pedroza DA demonstrated that PGRMC1 plays a prominent role in regulating the growth of cancer cells by altering the PI3K/AKT/mTOR and EGFR signaling mechanisms in both ER-positive and TNBC cells." (PMID 34746100, 2021). "Conversely, monounsaturated fatty acid (MUFA) contents decreased in cancer cells with PGRMC1 expression or P4 treatment but increased in PCC with shPGRMC1 vector transfection or AG205 treatment." (PMID 34749765, 2021). "This clearly reflects the complexity involved in assessing the relationship between expression of PGRMC1 and cancer-specific responses to various chemotherapeutic agents." (PMID 34885064, 2021). "Here, we showed that the natural active compound in licorice, glycyrrhizin (GL), directly binds to heme-dimerized PGRMC1 to inhibit PGRMC1-mediated EGF receptor (EGFR) activation in cancer cells." (PMID 34209885, 2021). "PGRMC1 is known to alter lipid metabolism and promote the proliferation and progression of cancer cells." (PMID 34749765, 2021).
cancer (continued). "Beside its classical function such as steroid hormone synthesis and metabolic function as a non-genomic progesterone receptor, the relevance between Pgrmc1 and cancers has been suggested in diverse organs." (PMID 34069911, 2021). "PPARγ is elevated in both ovarian and endometrial cancers and ligand activation of PPARγ increases PGRMC1 in adipocytes, making it likely that PPARγ is also involved in increasing PGRMC1 levels in reproductive cancer." (PMID 34885064, 2021). "Increased PGRMC1 expression is found in multiple types of resistant cancers, but the role of PGRMC1 in cancer cell ferroptosis remains unrevealed." (PMID 34749765, 2021). "In triple-negative MDA-MB-231breast cancer cells, which express PGRMC1 but lack expression of the classical P4 receptor, PGRMC1 decreased the apoptotic effects of doxorubicin." (PMID 34683909, 2021). "This study provides the first evidence of chemical compounds that directly bind to PGRMC1 to inhibit its function, and the findings provide new insights for cancer treatments that target PGRMC1." (PMID 34209885, 2021). "A significant amount of studies have reported that PGRMC1 is highly expressed in cancers including renal cell cancer, colon cancer, lung cancer, ovarian cancer, cervical cancer, breast cancer, and head and neck cancer." (PMID 34439295, 2021). "Another protein that increases cancer virulence is known as the progesterone receptor membrane component-1 (PGRMC-1), protein." (PMID 34830233, 2021). "Based on the binding activity of heme-dimerized PGRMC1, chemical screening with a natural product library revealed that several derivatives, including GlucoGL, exhibited more potent anti-cancer effects than GL." (PMID 34209885, 2021). "The in vitro antiproliferative efficacy of five common sigma ligands was investigated in the same panel of the 23 human established cancer cell lines in which we earlier investigated the expression levels of σ1, PGRMC1, and σ2/TMEM97 receptors." (PMID 33466391, 2021). "In this study, we identified PGRMC1 as a novel binding protein for GL and showed that GL exhibits its mediated anti-cancer effect by inhibiting PGRMC1 function, including EGFR activation and LDL uptake." (PMID 34209885, 2021). "Pgrmc1 is actively investigated for its possible rols in various cancers, but its relevance in HCC is poorly understood." (PMID 34069911, 2021). "Increased PGRMC1 expression is found in multiple types of resistant cancers, but the role of PGRMC1 in the ferroptosis of cancer cells remains unrevealed." (PMID 34749765, 2021). "Progesterone receptor membrane component 1 (PGRMC1) is highly expressed in cancer cells and enhances cancer proliferation and chemoresistance." (PMID 34209885, 2021). "In TNBC cells, PGRMC1 plays a prominent role in regulating the growth of cancer cells by altering the PI3K/AKT/mTOR and EGFR signaling mechanisms." (PMID 34746100, 2021). "This study shows that GL derivatives are novel compounds for directly binding with PGRMC1 to inhibit its anti-cancer function." (PMID 34209885, 2021). "We previously showed that suppression of PGRMC1 through knockdown significantly enhanced the cytotoxicity of cancer cells by anti-cancer agents, including the EGFR inhibitor erlotinib." (PMID 34209885, 2021). "We have previously shown that PGRMC1 forms a unique heme-stacking functional dimer to enhance EGF receptor (EGFR) activity required for cancer proliferation and chemoresistance, and the dimer dissociates by carbon monoxide to attenuate its biological actions." (PMID 34209885, 2021). "SIRT1 inhibition in parental cancer cells with PGRMC1 overexpression blocked autophagy, but SIRT1 activation in PCC with PGRMC1 inhibition induced autophagy, which was not affected by parthenolide treatment." (PMID 34749765, 2021).
cancer (continued). "We have previously shown that heme-dimerized PGRMC1 increases cancer resistance against anti-cancer drugs in HCT116 cells." (PMID 34209885, 2021). "Collectively, this study indicates that GL derivatives are novel inhibitors of PGRMC1 that suppress cancer progression, and our findings provide new insights for cancer treatment." (PMID 34209885, 2021). "Paclitaxel-tolerant persister cancer cells (PCC) had PGRMC1 upregulation related to increased free fatty acids, lipid droplets, and fatty acid oxidation." (PMID 34749765, 2021). "Chemical screening using GL derivatives revealed that the glucoside derivative glucoglycyrrhizin (GlucoGL) binds more potently to PGRMC1 and contributes to the suppression of PGRMC1-mediated cancer chemoresistance." (PMID 34209885, 2021). "Progesterone receptor membrane component 1 (PGRMC1) is highly expressed in various cancer cells and contributes to tumor progression." (PMID 34209885, 2021). "PGRMC1 expression has also been shown in several cancer cell, like in breast, prostate and lung, emphasizing the translational aspect of such findings." (PMID 33158280, 2020). "Progesterone receptor membrane component 1 (PGRMC1) has been shown to regulate some cancer hallmarks." (PMID 33076541, 2020). "This indicates that manipulation of the phosphorylation status of PGRMC1 Y180 can affect genomic stability, which is of potentially considerable relevance to cancer biology." (PMID 32293262, 2020). "Our data demonstrate that PGRMC1 plays a prominent role in regulating the growth of cancer cells by altering the PI3K/AKT/mTOR and EGFR signalling mechanisms in both ER-positive and TNBC cells." (PMID 32704174, 2020). "The use of MF as anti-cancer agent should be reconsidered in the light of its potential of tumor promoting action through activation of the PGRMC1 pathway." (PMID 33158280, 2020). "Our findings provide novel information that the use of MF as an anti-cancer agent should be considered with caution due to its potential PGRMC1 tumor-promoting pathway activation in cancers." (PMID 33158280, 2020). "Progesterone receptor membrane component 1 (PGRMC1) is often elevated in cancers, and exists in alternative states of phosphorylation." (PMID 32293262, 2020). "PGRMC1 protein has been reported to be overexpressed in several cancer cell lines and tissues, such as breast, thyroid, colon, ovary and lung." (PMID 32672400, 2020). "Recently, it has been demonstrated that PGRMC1 promotes tumorigenesis, cell proliferation, migration, invasion, and antiapoptosis in the same cancer types." (PMID 33158280, 2020). "For the first time, we also observed that PGRMC1 impacts on lipid rafts, another regulator of cancer progression." (PMID 32660617, 2020). "PGRMC1 is highly expressed in multiple types of cancer, and represents a proliferation marker for various cancer cells." (PMID 30679694, 2019). "A recent study revealed that the heme-mediated dimerization of adjacent PGRMC1 monomers in the cytoplasmic side leads PGRMC1 to interact with cytochromes P450 and EGFR, causing enhanced proliferation, anti-apoptosis, and chemoresistance of cancer cells." (PMID 30679694, 2019). "Subsequent studies showed that 108-B6 and 4A68, two of the MAbs, bind to cell surface expressed-PGRMC1 (csPGRMC1) on hPSCs and some cancer cells." (PMID 30679694, 2019). "This study provides insights into the potential oncogenic functional significance of PGRMC1 in cancer research." (PMID 31970154, 2019). "Previously, we generated two monoclonal antibodies (MAbs) 108-B6 and 4A68 that recognize cell surface-expressed PGRMC1 (csPGRMC1) on human pluripotent stem cells and some cancer cells." (PMID 30679694, 2019). "As a strong correlation between PGRMC1 expression and tumor progression has been confirmed, it has become a novel and promising target of the therapeutic intervention for cancer treatments." (PMID 31970154, 2019).
cancer (continued). "We believe all these findings uncover the potential of PGRMC1 as an oncogene and therapeutic target for human cancer patients who over-express this gene." (PMID 31970154, 2019). "The heme-mediated dimerization of adjacent PGRMC1 monomers leads PGRMC1 to interact with cytochromes P450 and EGFR, causing enhanced proliferation, anti-apoptosis, and chemoresistance of cancer cells." (PMID 29445107, 2018). "PGRMC1 is a multi-functional protein that is induced in various cancers and is critical for tumor growth, invasion and metastasis." (PMID 29445107, 2018). "Here we show that PGRMC1 is the target antigen of both MAbs, and is predominantly expressed on hPSCs and some cancer cells." (PMID 29445107, 2018). "Progesterone receptor membrane component 1 (Pgrmc1) is best characterized due to its role in cancer." (PMID 28362802, 2017). "Due to its correlation with tumor malignancy and progression, PGRMC1 becomes an attractive target of therapeutic intervention for cancer treatments." (PMID 28107520, 2017). "Progesterone receptor membrane component 1 (PGRMC1) is widely observed with an elevated level in multiple human cancers." (PMID 28107520, 2017). "The secreted PGRMC1 is a good biomarker for detecting the presence of cancer in a subject and for monitoring cancer progression by assaying its levels in a bodily fluid." (PMID 28107520, 2017). "In the current study, the Y113 residue plays a crucial role for the haem-dependent dimerization of PGRMC1 and resultant regulation of cancer proliferation and chemoresistance." (PMID 26988023, 2016). "We showed that haem-mediated dimerization of PGRMC1 enhances proliferation and chemoresistance of cancer cells through binding to and regulating EGFR and cytochromes P450." (PMID 26988023, 2016). "Such a dynamic structural regulation led us to further examine the regulation of PGRMC1 functions in cancer cells." (PMID 26988023, 2016). "The dimer is dissociated to monomers by physiological levels of CO, suggesting that PGRMC1 serves as a CO-sensitive molecular switch regulating cancer cell proliferation." (PMID 26988023, 2016). "Together, our data demonstrate PGRMC1 as a potential tumor biomarker across a variety of tumors, as well as a therapeutic target for cancer stem cells." (PMID 27867772, 2015). "The results support PGRMC1 as a tumor biomarker and therapeutic target for multiple types of cancer." (PMID 27867772, 2015). "In contrast, PGRMC1 inhibitors had activity against cancer stem cells, suggesting a role for PGRMC1 in maintaining cancer stem cell viability." (PMID 27867772, 2015). "PGRMC1 promotes cell survival and damage resistance in cancer cells and also plays roles in lipid, drug, and hormone metabolism in the liver and neuroprotection in the brain." (PMID 26042224, 2015). "In contrast, PGRMC1 inhibitors had activity against cancer stem cells, suggesting a role for PGRMC1 in cancer stem cell maintenance and the importance for inhibitors such as AG-205 for future therapeutics targeting cancer stem cells." (PMID 27867772, 2015). "This work suggests directions for further experiments that will be necessary to address the explicit role(s) of PGRMC1 in cancer." (PMID 18922159, 2008). "Furthermore, PGRMC1 expression was significantly correlated with cancer stage, tumor tissue subtype, and lymphatic metastasis status." (PMID 41153737, 2025). "By contrast, overexpression of PGRMC1 results in increased cell proliferation of cancer cell lines." (PMID 39464509, 2024). "Moreover, translocation of PGRMC1 induced by Ca2+ depletion leads to interaction with plasma membrane calcium channels, which promotes cancer cell migration and metastasis." (PMID 38804287, 2024). "Moreover, targeted bisulfite NGS methodology validated microarray data on four selected genes (GNL3L, FHL1, FLNA, and PGRMC1), confirming that they were hypomethylated in patients with cancer anorexia in comparison with controls." (PMID 39519555, 2024).
cancer (continued). "PGRMC1 was upregulated in all carcinoma groups, more in luminal A and TNBC, and vice versa." (PMID 39000458, 2024). "PGRMC1 is overexpressed in malignant cancer cells and localizes to mitochondria." (PMID 37651449, 2023). "Accumulating evidence indicates that PGRMC1 plays important roles in the biology of cancer as well." (PMID 37887342, 2023). "Our results also suggested that PGRMC1 may play a pivotal role in CRC progression, however, the molecular mechanism of PGRMC1 action in cancers is still not fully understood." (PMID 37894441, 2023). "As such, PGRMC1 could not only help cancer cells accumulate iron via hepcidin but also protect them from iron-induced cell death." (PMID 37834119, 2023). "If so, these putative progesterone modulators could find application not only as related to enhancing or inhibiting fertility but also for the treatment of ovarian and other cancers that express elevated levels of PGRMC1." (PMID 35626669, 2022). "However, progesterone can transmit its signal in MDA-MB-231 cells by binding to progesterone receptor membrane component 1, which has been shown to regulate some cancer hallmarks." (PMID 36232754, 2022). "This hypothesis is relevant to cancer biology, as it would imply that PGRMC1 overexpression in cancerous cells sustains the propagation of abnormal cancer cells, helping them to escape mitotic catastrophe." (PMID 36497237, 2022). "PGRMC1 expression levels in cancer tissue were significantly correlated with PGRMC1 in blood, PGRMC1 may be valuable as a new tumor marker and may be superior to known tumor markers." (PMID 34746100, 2021). "Importantly, the ABCC2 transporter was expressed at > 3-fold higher in PGRMC1-deplete tumors compared to control tumors and this transporter is highly effective in removing cisplatin from human cancer cells." (PMID 34885064, 2021). "Characterization of the heme–PGRMC1 regulatory pathway could potentially lead to novel therapeutic approaches for cancer and other diseases involving PGRMC1." (PMID 34439295, 2021). "Furthermore, they show that PGRMC1 dimerization is related to HCT116 cell chemoresistance to anti-cancer reagents erlotinib and doxorubicin." (PMID 34439295, 2021). "PGRMC1 has been deemed a novel tumor biomarker due to its elevated levels in human cancers." (PMID 34350123, 2021). "Therefore, we examined the role of PGRMC1 in promoting ferroptosis in paclitaxel-tolerant persister cancer cells (PCC)." (PMID 34749765, 2021). "Compelling evidence implies that PGRMC1 represents a promising target for cancer therapy." (PMID 34439295, 2021). "PGRMC1 may affect the functions of both normal and cancer cells, which might induce ferroptotic cell death in both." (PMID 34749765, 2021). "Tumors produced by both TM and Y180F cells were significantly smaller than those produced by WT or DM cells, indicating that PGRMC1 Y180 was required for optimal tumor growth, and demonstrating that the cellular responses to altered PGRMC1 phosphorylation strongly influences cancer biology." (PMID 32245408, 2020). "However, little is known about the relationship between PGRMC1 and cancer invasion, and how PGRMC1 functions in invasion." (PMID 32672400, 2020). "Additionally, we assessed the role of PGRMC1 in key cancer-related signaling pathways including EGFR/HER2 and ERα signaling." (PMID 32660617, 2020). "It is wholly feasible that characterization of the signal network surrounding PGRMC1 could lead to novel treatments for cancer, and other diseases involving PGRMC1." (PMID 32293262, 2020). "Some studies have also shown that PGRMC1 is expressed on the surface of cancer and neuronal cells." (PMID 30679694, 2019). "Furthermore, to determine the general significance of the oncogenic and prognosis role of PGRMC1, we investigated the over-expression and prognosis value in many different cancer types." (PMID 31970154, 2019). "Besides, the over-expression and unfavorable prognosis value of PGRMC1 were also observed in many other cancer types." (PMID 31970154, 2019).